CD4 (CD4 molecule)
Diseases named in the same sentence as CD4 in open-access papers (continued):
Sharing a sentence is not in itself a finding about the gene and the disease.
colon carcinoma (continued). "Detection results of peripheral blood mononuclear cells in 20 patients showed that the antigenic immune response of colon cancer was enhanced, and the inhibitory regulatory T lymphocytes (CD4+ CD25T-reg+) were significantly reduced." (PMID 37124541, 2023). "In Table-IV, it was detected that the levels of CD4+, CD8+ and CD4+/CD8+ ratio were incomplete identical in peripheral blood of patients with □-□ colon cancer." (PMID 37492300, 2023). "Simultaneously, the count of CD4+ cells and the ratio of CD4+/CD8+ in lymphocyte subsets of colon cancer patients were lower than that of the control group, while the count of CD8+ cells was higher than that of the control group." (PMID 37492300, 2023). "CD4 memory resting cells can play a dual role in both the immune response to cancer cells as well as the development and progression of colon cancer." (PMID 37465677, 2023). "We next investigated the CD46-9652-ES and PSMC5-43011-ES levels in 20 colon cancer samples characterized by CD4+/CD4- T cell infiltration and 20 colon cancer samples characterized by high/low M2 macrophage infiltration." (PMID 35692800, 2022). "GGH was upregulated in colon cancer; its high expression was correlated with CD4+ T cell infiltration and longer overall survival and it was identified as a favorable independent prognostic factor." (PMID 36569910, 2022). "Aside from Th1 cells, other human colon cancer-infiltrating CD4+ T-cell subsets, including Th17 cells, Th22 cells, and Tregs, can express IFNγ." (PMID 34385592, 2022). "Expression of MHC class II, but not MHC class I, confers responsiveness to anti-PD-1 therapy in colon cancer and B and T cell lymphoma models via cytotoxic CD4 T cells." (PMID 35565329, 2022). "The increased levels of pro-inflammatory cytokines (TNF-& IL-1β), and tumor markers (CEA, CA19.9 and AFP) matched with a decrease in apoptotic biomarkers (CD4+) in colon cancer-bearing rats are in line with other earlier research." (PMID 36294905, 2022). "EpCAM and PD-L1 were also found to be upregulated in CD4+ T cells derived from colon cancer patients, which was regarded as an ineffective immune response." (PMID 36369033, 2022). "In colon cancer, the highest correlation was found between CD4+ T cells and RPS14 (correlation = −0.5) and CD4+ T and RPS15A (correlation = −0.49), as well as dendritic cells and RPS3 (correlation = −0.49)." (PMID 35127345, 2022). "In order to further confirm which T cell subtype plays a key role in tumor control, we performed CD8+ T cell and CD4+ T cell depletion experiments on a postsurgical colon cancer mouse model." (PMID 35595770, 2022). "Dramatically, ILC3s expresses the major histocompatibility complex class II (MHC II) to drive type-1 immunity that inhibits microbiota-specific effector CD4+ T cell responses, which is sensitive to anti-PD-1 immunotherapy in colon cancer." (PMID 35684019, 2022). "A positive association was found between the expression level of ABCA5 and the infiltration levels of B cells, CD8+ T cells, CD4+ T cells, macrophages, neutrophils, and dendritic cells in colon cancer tissues (P < 0.05)." (PMID 35783152, 2022). "CD4 T cells promote colon cancer stemness via the regulation of stemness genes, which negatively affects patient outcome." (PMID 36146640, 2022). "The infiltration levels of all TIICs, including B cells, CD4+T cells, CD8+ T cells, neutrophils, macrophages, and dendritic cells, were favourably linked with the expression of KLF3, KLF5, and KLF6 in colon cancer." (PMID 35345512, 2022). "It is negatively correlated with B cells in rectal cancer and positively correlated with CD4+ T cells in colon cancer." (PMID 36553482, 2022). "The results showed that low-dose decitabine-treated CD4+ T cells exhibited an elevated cytotoxicity against mouse colon carcinoma MC38 cells as compared with control CD4+ T cells." (PMID 33791306, 2021).
colon carcinoma (continued). "We first separated CD4+ T cells from PBMC of colon cancer patients, and the isolated CD4+ T cells always remained above 90 %." (PMID 33468159, 2021). "Our study implied that TGFβ1 greatly participated in the modulation of the colon cancer TIME through communicating with T cells CD4 naïve and Tregs." (PMID 33995472, 2021). "Using the TIMER 2.0 database, we also demonstrated that TNFRSF11B negatively affected the infiltration of activated memory CD4+ T cells into the colon cancer microenvironment (cor = −0.158, p = 0.008)." (PMID 34938284, 2021). "In our study, we observed the immunosuppressive role of TNFRSF11B in the regulation of memory CD4+ T cell activation in colon cancer tissue and peripheral blood monocytes, and our findings were validated in TCGA-COAD datasets." (PMID 34938284, 2021). "Among these TIIC subtypes, macrophages (M1 + M2) accounted for approximately 38%, neutrophils accounted for approximately 32%, CD4+ T cells accounted for 10% and NK cells accounted for 7% in colon cancer tissues." (PMID 35096572, 2021). "Analysis of tumor infiltration indicated increased infiltration by CD8+ and CD4+ T cells in the high-mRNAsi group of colon cancer." (PMID 34568334, 2021). "The expression of GNAI2 in CD11c+ cells and IL6 in CD4+/CD11b+ DCs appears to promote colon tumor development in mice." (PMID 33828969, 2021). "In the colon cancer model, the loss of GARP in Treg leads to spontaneous inflammation and enteritis with high activation of CD4+ and CD8+ T cell, which has an important impact on immune surveillance." (PMID 34421887, 2021). "The CD8+ T cells were more strongly negatively correlated with mast cells and resting memory CD4+ T cells in the high-mRNAsi group than the low-mRNAsi group of colon cancer patients." (PMID 34568334, 2021). "CD8+ cells were linked to improved survival in colon cancer stages I-III (q = 0.014), while CD4+ cells had the strongest impact on overall survival in metastatic CRC (q = 0.031)." (PMID 34771707, 2021). "To further study the anti-tumor capacity of low-dose decitabine-pretreated CD4+ T cells in vivo, we performed a tumor-bearing xenograft model of mouse colon cancer MC38 cells and transferred low-dose decitabine-pretreated CD4+ T cells." (PMID 33791306, 2021). "Subgroup analyses showed that the association of CD4+ T cells with CRC prognosis was statistically significant in stage I–III and colon cancer patients." (PMID 34204621, 2021). "The most researched ligand has been CCL16 whose increased expression has shown an anti-cancer effect in mouse breast cancer, and colon carcinoma, and prostate cancer due to an increase in the infiltration of the tumor by CD4+ T cells, CD8+ T cells, and DC." (PMID 33182504, 2020). "Abnormal levels of epithelial cell adhesion molecule (EpCAM)+CD4+ T cells were observed in colon cancer patients." (PMID 33135337, 2020). "HIF-1α itself plays an important role in the modulation of CD4+ T cell functions under hypoxic conditions in colon cancer mice cell cultures and can decrease T cell immunity." (PMID 32033172, 2020). "To investigate the role of BATF3-dependent DCs in a model of T-cell driven anti-tumor immunity, we took advantage of the highly immunogenic MC38 colon cancer xenograft model, which is known to be strictly controlled by both CD4+ and CD8+ T-cells." (PMID 31188899, 2019). "A recent study of human colon cancer identified a CD4+ TIL Th1 subset with elevated Bhlhe40 expression." (PMID 31801070, 2019). "One microsatellite-stable colon cancer patient achieved durable partial response showing increased infiltration of both CD4+ and CD8+ T cells into tumors after IT1208 administration." (PMID 31340866, 2019). "In humans it has been shown that the magnitude of CD4 T cells in microsatellite-unstable (MSI-H) colon carcinomas is significantly higher in HLA class II-negative tumors harboring mutations in HLA class II-regulatory genes such as RFX5, CIITA, and RFXAP." (PMID 29032503, 2018).
colon carcinoma (continued). "The regulatory cells (like CD4 and CD25) are capable of reducing the severity of inflammatory bowels and lower the risk of colon cancer." (PMID 29568324, 2018). "Treating PBMCs isolated from colon cancer patients with VIPhyb and idelalisib increases the polyfunctionality strength index of CD4+ T cells." (PMID 30400835, 2018). "(D and E) Immunofluorescence of CD4 (D) and IL-17 (E) in infected colons showing enhanced Th17 cells infiltrating in miR-34a-/- colonic tumors." (PMID 30543324, 2018). "In our study, we found specific DNA hypomethylation of FOXP3-TSDR in CD4+ T cells from colon tumor tissues as compared with normal colonic tissues." (PMID 30013992, 2018). "The FOXP3-TSDR was found to be significantly hypomethylated in CD4+ T cells from colon tumor tissues as compared with normal colonic tissues." (PMID 30013992, 2018). "To confirm that the abnormally increased STAT5 and TET2 bind more strongly to FOXP3-TSDR in CD4+ T cells from colon tumor tissues compared with which from normal tissues, we performed ChIP-qPCR analysis using anti-STAT5 and TET2 antibody." (PMID 30013992, 2018). "We measured the mRNA and protein expression levels of STAT5 and TET2 in CD4+ T cells from colon tumor tissues coupled with corresponding normal colonic tissues." (PMID 30013992, 2018). "In order to validate the interaction between STAT5 and TET2, we performed coimmunoprecipitation using anti-STAT5 in CD4+ T cells from colon tumor tissues." (PMID 30013992, 2018). "The results showed that FOXP3 mRNA and protein levels were sharply increased in CD4+ T cells from colon tumor tissues." (PMID 30013992, 2018). "In the murine model of colitis-associated colon cancer (CAC), CD4+ Foxp3+ Tregs are crucial for the control of the inflammatory process." (PMID 28938014, 2017). "In human colon cancer, many researches have showed increased CD4+CD25high FoxP3+ Treg cells in peripheral blood mononuclear cells (PBMCs) and draining lymph nodes, which can suppress antigen-specific CD4+ T cells." (PMID 29312592, 2017). "Loxoribin, a TLR7 agonist, inhibited tumor growth using xenograft models for both lung and colon cancer, both mediated by promoting CD4+ T cells and activating dendritic cells." (PMID 29190881, 2017). "Activity tests showed that Se-CEPS improved the immune organ index, serum cytokine content, and CD8+ and CD4+ T lymphocyte ratio in colon cancer CT26 tumor-bearing mice, thereby inhibiting tumor growth." (PMID 27347005, 2016). "Colon neoplasms and surrounding microenvironment tissues of mice administered anti-G-CSF were stained for CD4+ T cells." (PMID 26061815, 2015). "In the lung metastasis model, we found that combination-treated CT26 colon tumor bearing mice had a lower percentage of Treg cells amongst CD4+ T cells in the spleen, in comparison with IL-7 alone, OXP alone, and control mice (P<0.05)." (PMID 24465710, 2014). "It has been shown that the numbers of CD4+CD25+Foxp3+ Tregs are increased in the peripheral blood mononuclear cells (PBMCs) and draining lymph nodes of human colon cancer patients, and these Tregs are capable of suppressing antigen-specific CD4+ T cells." (PMID 24637664, 2014). "The surgical removal of colon cancer reduces the Treg population and restores the antigen-specific T cell activity of CD4+ T cells." (PMID 24637664, 2014). "Similar to these observations made in primary colon tumors, the presence of increased CD4 and CD8 T cell infiltrates identified by immunohistochemistry in CRLM has also been associated with improved recurrence free and overall survival." (PMID 23514280, 2013). "We also showed that MUC1-specific CD4+ T cells played critical roles in the rejection of MUC1-expressing colon carcinoma cells in B6 mice vaccinated with MUC1 cDNA." (PMID 23028615, 2012). "To better understand the homing mechanisms involved in T cell migration to colon tumors we examined homing receptor expression on CD4+, CD8+ LPL and Treg." (PMID 22319577, 2012).
colon carcinoma (continued). "In contrast to human colon cancer in which the rate of tumor infiltrating lymphocytes is less than 10% of surrounding stromal cells, we found a much higher number of primarily CD4+ T cells." (PMID 20205946, 2010). "The influence of CD4+CD25+ cells on immune responses against human colon cancers is under investigation in the laboratory." (PMID 16641897, 2006). "Importantly, CD4+T cells have been demonstrated to be the most abundant lymphocyte population in the TME of murine metastatic colon cancer system." (PMID 41181711, 2025). "PMFs increase CD4+ T cell infiltration in colon cancer tissues." (PMID 40290432, 2025). "The study also revealed that “CD25hi CD45RA+ CD4 not Treg AC” was causally related to rectal cancer and colon cancer, and “CD27 on unsw mem” to rectal cancer and cancer of the small intestine." (PMID 38533503, 2024). "Of these, chr22-38_28785274-29006793.1 might be of the greatest importance, as it is significantly associated with tumor-infiltrating CD4+ and CD8+ T cells in invasive breast and colon cancers." (PMID 36816359, 2023). "TOMM34 expression was positively associated with the infiltration of CD4+ T cells and was not correlated with macrophages in colon cancer." (PMID 36845719, 2023). "In contrast, in advanced-stage colon cancer, the pro-tumor effects of CD4 memory resting cells may outweigh their anti-tumor effects, resulting in a poorer prognosis." (PMID 37465677, 2023). "Furthermore, GGH expression was positively related to the infiltration of CD4+ T cells in colon cancer in clinical samples." (PMID 36569910, 2022). "Regarding the effect of TGFβ on colon tumor-infiltrating CD4+ T cells, the increased presence of TGFβ in sporadic colon tumors was obviously accompanied by the augmented presence of IL-17A+ IL-22+ CD4+ T cells." (PMID 36428508, 2022). "Further analysis indicated that p38/MAPK might be a potential target for EpCAM+/CD4+ T-cell-rich colon cancer patients." (PMID 36369033, 2022). "Based on large-scale bioinformatics analysis, we discovered that elevated PBK/TOPK expression predicted a favorable outcome in patients with colon cancer and was positively associated with immune infiltration levels of CD8+ T cells, CD4+ T cells, natural killer cells, and M1 macrophages." (PMID 35203508, 2022). "To see whether enhanced anti-tumor immunity in vivo is related to the absence of CDK6 in T cells, we subcutaneously injected Cdk6fl/fl CD4-Cre and Cdk6fl/fl mice with the colon carcinoma cell line MC38, which is surveilled by CD8+ T cells." (PMID 34248938, 2021). "Similarly, endogenous IL-33 promoted the expansion of IFN-γ+CD4+ T cells in tumor mouse models for colon carcinoma and hepatocellular carcinoma." (PMID 34209038, 2021). "Furthermore, the association of CD4+ T cells and prognosis was stronger among patients with early or intermediate CRC or patients with colon cancer." (PMID 34204621, 2021). "In subsite specific analyses, the association of a higher proportion of CD4+ T cells with better survival was statistically significant among colon cancer patients but not rectal cancer patients, of whom the sample size was smaller." (PMID 34204621, 2021). "Moreover, we observed that NF-κB inhibitor decreased the cytotoxicity of decitabine-treated CD4+ T cells against colon cancer MC38 cells." (PMID 33791306, 2021). "In addition, low-dose decitabine enhanced the cytotoxicity of CD4+ T cells against colon cancer HCT116 cells, and increased CD107a expression." (PMID 33791306, 2021). "Finally, we shed light on the suppressive role of TNFRSF11B in the tumor infiltration of activated memory CD4+ T cells in colon cancer." (PMID 34938284, 2021). "Similarly, IL-33 was reported to amplify IFN-γ+ CD4+ T cells in mouse models of hepatocellular and colon carcinoma." (PMID 33329534, 2020).
colon carcinoma (continued). "In some cancers, an increased expression of CCR4 ligands (CCL17 and CCL22) in a tumor may play an anti-tumor role in colon carcinoma, lung cancer, ovarian cancer and melanoma, resulting in an increase in CD4+ T cells and CD8+ T cells." (PMID 33182504, 2020). "Oberg showed that in patients with colon cancer, higher percentages of CD4+ memory T cells may be indicative of a better prognosis." (PMID 32850314, 2020). "CD4+ and CD8+ T cell-related genes associated with colon cancer prognosis." (PMID 32571262, 2020). "ELK3, which was down-regulated in cancer tissues, may be correlated with colon cancer and CD4+ T cells." (PMID 32571262, 2020). "As such, analyses of the molecular mechanisms underlying the roles of CD4+ and CD8+ T cells in colon cancer may provide novel targets for immunotherapy." (PMID 32571262, 2020). "Therefore, we analyzed the molecular mechanisms associated with CD4+ and CD8+ T cell activity in colon cancer to explore the potential benefits of immunotherapy." (PMID 32571262, 2020). "To investigate the relative proportions of immune infiltrates in the colon cancer risk subgroups, we compared the abundance of immune cell subpopulations including CD8+ T cells, CD4+ T cells, dendritic cells, neutrophils, B cells, and macrophages in the TIMER database." (PMID 33425745, 2020). "TILs were expanded with the REP (rapid expansion protocol) from tumoral or inflamed/normal prostate (n = 8), colon cancer metastasis (n = 4) and metastatic melanoma (n = 6); cell cultures with heterogeneous CD4+/CD8+ T cell ratios were obtained according to the tumor evaluated." (PMID 31601268, 2019). "Finally, TDEs isolated from KRAS mutant (MT) human colon cancer cells can induce conventional CD4+ CD25− T cells to convert to Tregs (CD4+ CD25+ FOXP3+) in a cell-extrinsic manner." (PMID 31635338, 2019). "To investigate whether the FOXP3-TSDR was aberrantly DNA methylated in CD4+ T cells from colon tumor tissues, we did bisulfate sequencing analysis for TSDR." (PMID 30013992, 2018). "As such, B cells, CD4+, and CD8+ T cells have been associated with improved clinical outcomes whereas regulatory cell types, such as regulatory T cells and neutrophils, have been associated with poor outcome in ovarian, breast, lung, and colon cancers." (PMID 30382883, 2018). "Moreover, we also found that the expression of STAT5 and TET2 was increased in CD4+ T cells from colon tumor tissues, and the superfluous STAT5 and TET2 binding to FOXP3-TSDR resulted in DNA hypomethylation." (PMID 30013992, 2018). "The heatmaps of CD44 mRNA in colon cancer were strikingly opposite to CD4 and CD74." (PMID 27323782, 2016). "In this study, we confirmed CD44 was strikingly opposite to CD4 in colon cancer." (PMID 27323782, 2016). "Our present results extend these findings to another major type of gastrointestinal tumors, showing that also in colon tumors there are decreased frequencies of CD4+ conventional T cells and Treg expressing α4β7 and a concomitant decrease in MAdCAM-1 expression on the blood vessels." (PMID 22319577, 2012). "However, two studies compared these regulatory cells in prostate and colon cancers, and both studies acknowledged that CD4 Treg cells and CD8 Treg cells were similar in their suppressive function." (PMID 23152910, 2012). "However, Treg and conventional CD4+ T cells expressing CCR4, which is primarily expressed on Th2 type CD4+ T cells and Treg were accumulating in the colon tumors." (PMID 22319577, 2012). "The absence of mMGL1 receptor also appears to contribute to reducing the expansion of M‐MDSC in the tumor microenvironment; consequently, the percentages of CD4+ and CD8+ T cells increased, which may be associated with the lower number and size of colon tumors in Mgl1−/− CAC mice." (PMID 40033767, 2025).